CRP (C-reactive protein)
Diseases named in the same sentence as CRP in open-access papers (continued):
Sharing a sentence is not in itself a finding about the gene and the disease.
COVID-19 (continued). "The level of CRP was significantly higher in COVID-19 symptomatic compared to asymptomatic pediatric patients (p = 0.003)." (PMID 34150833, 2021). "Patients who died of COVID-19 had significantly higher median CRP levels during whole observational period compared to patient who recovered." (PMID 34476598, 2021). "C-reactive protein (CRP) has prognostic value in hospitalized patients with COVID-19; the importance of CRP in pre-hospitalized patients remains to be tested." (PMID 35011944, 2021). "The prognostic value of IL-6 and C-reactive protein for COVID-19 severity has already been described." (PMID 33572045, 2021). "Within the COVID-19 group, older age (mean age 65), (p=0.014), elevated CRP (p=0.012), low O2 saturation (p=0.001), and beta blocker use (P=0.01) were associated with increased mortality." (PMID 34414048, 2021). "Low albumin levels, high C-reactive protein levels, a high leukocyte count, and low lactate dehydrogenase levels make the model more likely to predict a critical/severe COVID-19 case." (PMID 33534723, 2021). "Common clinical findings of COVID-19 include leukopenia and lymphopenia, as well as abnormalities that include elevated levels of aminotransferases, C-reactive protein, D-dimer, ferritin, and lactate dehydrogenase." (PMID 35083164, 2021). "Nearly all biological covariates reflecting COVID-19 severity were associated with death, including admission plasma glucose, plasma creatinine, AST, white cells, lymphocyte and platelet counts and CRP level." (PMID 33599800, 2021). "The most common laboratory findings in COVID-19 patients are elevated CRP levels, decreased albumin levels, increased ESR, lymphopenia, eosinopenia, increased IL-6, and increased LDH." (PMID 34445855, 2021). "In influenza, the white blood cell count, C-reactive protein (CRP), procalcitonin, and bilirubin were increased, while in COVID-19 the number of platelets was significantly increased." (PMID 33613111, 2021). "Older COVID-19 patients, who developed cerebrovascular disorder, possess high levels of D-dimer and C-reactive protein (CRP) and are at a hyper-coagulation condition." (PMID 33456304, 2021). "If patients had a C-reactive protein (CRP) ≥ 200 mg/l, there was a high potential for benefit of corticosteroids in COVID-19 ARDS with a lower mortality (OR 0.23; 95% CI 0.08–0.70)." (PMID 34034789, 2021). "Items with higher scores are more common in COVID-19 patients, such as fever, abnormal chest CT, and normal levels of CRP and WBC." (PMID 33996842, 2021). "We also found elevated plasma levels of IFN-γ, IL6, and C-reactive protein in samples from COVID-19 patients." (PMID 35062250, 2021). "Some inflammatory biomarkers have been considered as tools to monitor the evolution of COVID-19, namely C reactive protein (CRP), lactate dehydrogenase (LDH), ferritin and D-dimer." (PMID 34172816, 2021). "CRP has been well reported to be a prognostic indicator of disease severity and respiratory decline in COVID-19 patients." (PMID 34714894, 2021). "Novel studies have suggested that analyzing the CRP and lymphocyte counts revealed the efficacy of treatment of COVID-19." (PMID 32892540, 2021). "Specifically, hs-CRP levels in patients with mild, moderate, and severe COVID-19 were more than 22-, 34-, and 82-fold higher than the respective control values." (PMID 33920813, 2021). "Red cell distribution width, platelet distribution width, and C-reactive protein are useful early predictive markers of mortality in COVID-19." (PMID 33680618, 2021). "The results indicated that there were positive correlations between renal dysfunction with IL-6 and CRP in COVID-19 patients." (PMID 33557785, 2021). "In conclusion, our double-center cohort analysis demonstrates that among patients hospitalized with moderate to severe COVID-19, older age, lymphopenia, and elevated CRP were independent predictors of hypoxemia and respiratory-related adverse outcomes." (PMID 34441877, 2021).
COVID-19 (continued). "Available data suggests CRP is often higher in COVID-19 patients with worse outcomes 10, which is also observed in our study." (PMID 33967613, 2021). "Recombinant anti-MASP2 (Narsoplimab), which inhibits lectin pathway activation, has been tested as a COVID-19 therapeutic, resulting in rapid reduction in inflammatory and cell death markers (CRP, IL-6, IL-8, LHD) in six treated patients with ARDS." (PMID 34930107, 2021). "In the context of COVID-19, an increase in CRP concentration is also often described, and its concentration, according to some reports, correlates with the severity of COVID-19." (PMID 34575258, 2021). "The cytokine storm is common in severe to critical cases of COVID-19, along with concomitant reductions in natural killer cells (NK) and lymphocyte cell counts, and increases in levels of C-reactive protein (CRP), D-dimer, procalcitonin and ferritin." (PMID 34831321, 2021). "Further studies on the correlation of C-reactive protein and thrombotic events in COVID-19 patients would provide a better sense of the importance of using this lab test in the care of COVID-19 patients." (PMID 34035963, 2021). "In COVID-19 patients, we found that the levels of C-reactive protein and lactose dehydrogenase were obviously higher in critical patients than in other patients." (PMID 33986253, 2021). "Recent studies highlight the importance of biomarkers like D-Dimer, anticardiolipin IgG autoantibody, C-reactive protein, and interleukin-6 in the prediction of COVID-19 patients’ clinical decline." (PMID 34070021, 2021). "Clinical variables, Charlson Comorbidity Index (CCI), C-reactive protein (CRP), CAC (COVID-19-associated coagulopathy), defined according to the ISTH score, treatment and in-hospital events were collected." (PMID 34068127, 2021). "The initial CRP of severe COVID-19 patients increased prior to CT findings, and the CRP value increased rapidly after admission, indicating a strong inflammatory response; the virus is prevalent in patients' bodies at this stage." (PMID 33834012, 2021). "Previous studies investigated different biomarkers such as C-reactive protein (CRP), interleukin (IL)-6, procalcitonin (PCT), etc. in COVID-19 patients and their association with disease progression." (PMID 34895167, 2021). "In the field of laboratory tests, patients with COVID-19 were characterized by a higher level of fibrinogen and CRP and a lower level of HGB, platelet, and WBC counts." (PMID 34408718, 2021). "Increase in ESR, Anti-CCP, IL-6 and CRP has been reported in patients who had been affected by COVID-19 with history of RA." (PMID 34181704, 2021). "Reports of children hospitalized with COVID-19 suggest similar clinical inflammatory profiles, including elevated c-reactive protein (CRP), ferritin, procalcitonin (PCT), and reduced ALC." (PMID 33653907, 2021). "They enrolled 149 COVID-19 positive patients and found that cardiac Troponin I levels were in significant correlation with ferritin levels, IL-6, IL-8 and high-sensitivity CRP." (PMID 34300181, 2021). "Apart from these, macrophage inflammatory protein (MIP)-1α, monocyte chemoattractant protein (MCP)-1, C-reactive protein (CRP), G-CSF, procalcitonin, and ferritin were noticed in COVID-19 patients." (PMID 33981235, 2021). "In COVID-19 patients as well as in critically ill patients, increased plasma inflammatory markers such as CRP have been well described." (PMID 33562403, 2021). "Correlations between AT and intact ITHI4 and CRP were also significant when only the first collected samples post COVID-19 diagnosis were analysed." (PMID 34458849, 2021). "We have demonstrated that CRP follows a bimodal distribution in hospitalized patients with COVID-19." (PMID 33683344, 2021). "Advanced age, together with impaired renal function and elevated C-reactive protein have been reported as major predictors of in-hospital death in a large cohort COVID-19 patients in Italy." (PMID 33556127, 2021).
COVID-19 (continued). "Anti-C1q has been found to be elevated in hospitalised COVID-19 patients and CRP is routinely elevated in patients who have severe and/or fatal outcomes." (PMID 34930107, 2021). "The current study focused on the levels and prognosis of seven indicators including oxygen, lymphocytes, albumin, leukocyte, CRP, IL-6, and D-dimer in COVID-19 patients." (PMID 34778296, 2021). "Patients with LTBI-COVID-19 co-infection had higher lymphocyte and monocyte counts, along with lower NL ratio, CRP, and ALT levels." (PMID 34966601, 2021). "The comparison of CRP between patients with influenza-B and COVID-19 showed similar results (26.1 mg/L vs. 4.8 mg/L, p < 0.05)." (PMID 34859002, 2021). "Out of all the patient characteristics, only obesity independently affected the blood levels of peak-CRP in COVID-19 patients." (PMID 34178545, 2021). "First, the present data demonstrated that older age, obesity, lymphopenia, and elevated CRP were independent predictors of hypoxemia that occurred early after hospitalization with COVID-19." (PMID 34441877, 2021). "Hyperglycemia was also an independent predictor of a high leucocyte count (OR 4.14, 95% CI 1.61-10.64), NLR (OR 3.23, 95% CI 1.49-7.04), and CRP level (OR 2.76, 95% CI 1.33-5.72) in patients with COVID-19." (PMID 33814982, 2021). "Significant increased CRP levels in the early stages of COVID-19 are correlated with the severity of disease and the degree of internal tissue pathologies." (PMID 33872186, 2021). "CRP level is an indicator for assessing inflammation, and elevated CRP has been found to be present in 60.7% of adult COVID-19 patients, particularly in severe cases." (PMID 34631608, 2021). "In multivariate analysis, elevated levels of troponin [OR 1.54; (95% CI 1.22–1.96), p < 0.001)], IL-6 [OR 1.69 (95% CI 1.26–2.27), p < 0.013)], and CRP [OR 1.32; (95% CI 1.1–1.58), p < 0.003)] were predictors of mortality in patients with COVID-19." (PMID 33211155, 2021). "Our study shows that in critically ill COVID-19 patients, the inflammatory biomarkers CRP and PCT show a rebound increase upon cessation of dexamethasone treatment, potentially leading to false-positive findings." (PMID 34353339, 2021). "Further, in the hypertensive group, COVID-19 patients with increased CRP or hs-CRP presented an increased level of cardia injury markers, LDH (p < 0.001), CK (p = 0.07) and CK-MB (p = 0.09)." (PMID 34789776, 2021). "Procalcitonin (PCT) and C-reactive protein (CRP) were previously shown to have value for the detection of secondary infections in critically ill COVID-19 patients." (PMID 34353339, 2021). "COVID-19 patients had normal or decreased white blood cell counts, decreased lymphocyte counts, and increased C-reactive protein." (PMID 34796234, 2021). "The results of this large, randomised trial indicate that tocilizumab is an effective treatment for hospitalised COVID-19 patients who have hypoxia and evidence of inflammation (CRP ≥75 mg/L)." (PMID 33933206, 2021). "The C5 inhibitor eculizumab resulted in recovery and reduced mean CRP levels in four patients with COVID-19, although the global Phase 3 clinical trial evaluating the longer-acting C5 inhibitor ravulizumab was recently discontinued for lack of efficacy." (PMID 34924021, 2021). "In this sense, the CRP-to-albumin ratio better predicts the severity of COVID-19 than CRP or serum albumin separately." (PMID 34683480, 2021). "Acute serum IL-6 and CRP levels were then compared to those with suspected COVID-19 (SCOVID) and age and sex matched patients with SAB and patients hospitalized for any non-infectious condition (NIC)." (PMID 33815405, 2021). "The current study revealed that severe COVID-19 patients had low serum AAT levels related to CRP values." (PMID 34007243, 2021). "Patients with higher NRS scores tend to have more severe COVID-19, higher C-reactive protein and serum procalcitonin levels, higher white blood cell counts, lower lymphocyte counts, and higher mortality rates (P < .05)." (PMID 33832097, 2021).
COVID-19 (continued). "Some recent studies noted that COVID-19 is linked with the cytokine storm, pneumonia, ARDS, C-reactive protein (CRP), and heart failure." (PMID 34894332, 2021). "Patients who died from COVID-19 had a higher C-reactive protein and lower lymphocytic count than the recovery group." (PMID 33441572, 2021). "Various abnormal hematological parameters including leukocytosis, neutrophilia, thrombocytopenia, lymphopenia, elevated CRP, procalcitonin, D-dimer, and fibrinogen levels have been shown in many studies conducted with COVID-19 patients." (PMID 34868686, 2021). "Several studies reported typical patterns of laboratory tests in patients with COVID-19 and some independent predictors of disease severity and mortality, such as C-reactive protein (CRP), ferritin, and D-dimer, were identified." (PMID 33620680, 2021). "Despite the depletion of the T cells, massive destruction in the lungs is found along with the extreme levels of CRP in the aggravated COVID-19 patients." (PMID 33679775, 2021). "For example, CRP levels were independent discriminators of severe/critical illness on admission and a good predictor of adverse outcome in COVID-19 patients." (PMID 34300279, 2021). "The relationship of CRP to COVID-19 (+) is well documented, but due to the inflammatory nature of the disease and therefore an overall increase in CRP, its utility as a marker of post-COVID depression requires further investigation." (PMID 34575258, 2021). "We also report pre-COVID-19 levels of CRP – only when measured during the same blood drawing as RDW—which were significantly higher upon admission for COVID-19." (PMID 33816532, 2021). "We verified that the ratio between platelets/neutrophils, platelets/NTL, platelets/CRP, platelets/creatinine, and platelets/urea provided a statistically significant biomarker for the prediction of death due to COVID-19." (PMID 34685377, 2021). "The Infectious Diseases Society of America has recommended that the criteria for systemic inflammation in COVID-19 patients be a CRP value of ≥75 mg/L, and that such patients be given both dexamethasone and monoclonal antibody therapy." (PMID 34111164, 2021). "Tocilizumab is an mIL-6R and sIL-6R inhibitor that reverses the increases in serum CRP and IL-6 levels in patients with COVID-19." (PMID 33404925, 2021). "Neutrophil-to-lymphocyte ratio and systemic inflammatory markers like CRP have been used as an early predictor of COVID-19 severity." (PMID 33651717, 2021). "A severity score consisting of age, oxygen saturation, mean arterial pressure, blood urea nitrogen, C-reactive protein, and the international normalized ratio was shown to improve prediction of COVID-19-related in-hospital mortality." (PMID 33972591, 2021). "In summary, male patients had higher neutrophil, CRP, and inflammatory cytokine levels, and lower lymphocyte levels, which were related to the poor prognosis and severe clinical symptoms of male COVID-19 patients." (PMID 34225644, 2021). "Differences have been shown between COVID-19 studies regarding the significance of sensitivity of CRP values in determining disease prognosis." (PMID 33315349, 2021). "This first trial of tocilizumab in critically ill patients with COVID-19 resulted in successful outcomes; it improved the clinical symptoms and CRP concentrations of the treated patients." (PMID 34253862, 2021). "Among the 140 investigated COVID-19 patients, 91 (65%) patients showed increased CRP levels, and these were more significant in the severe group than the mild group." (PMID 33808934, 2021). "In a study of 200 hospitalised patients with suspected COVID-19, Mardani, Ahmadi and Vasmehjani suggested lactate dehydrogenase, C-reactive protein, alanine aminotransferase, and neutrophil count were useful for diagnosing COVID-19." (PMID 33946171, 2021). "Various studies have suggested that higher levels of inflammatory markers such as WBC, CRP, PCT, ESR, IL-6, andIL-10 are associated with the severity of COVID-19." (PMID 35539890, 2021).
COVID-19 (continued). "From a laboratory point of view, our data show that the level of CRP is increased in the pre-operative period in COVID-19 + patients." (PMID 35011909, 2021). "Until now, the therapeutic option of reducing the extremely high amount of CRP has been used once in the early phase of COVID-19 and in end-stage patients with one case being reported." (PMID 33679775, 2021). "Raised neutrophil-lymphocyte ratio, mean platelet volume, IL-6, D-dimer, serum ferritin, LDH, and CRP were important prognostic markers in determining the severity of COVID-19." (PMID 34966605, 2021). "In the non-COVID-19 patients, even their plasma level of CRP was above 60–180 mg/L, their TYMP expression was still significantly lower than in the COVID-19 patients with CRP < 20 mg/L (p = 0.025)." (PMID 33829029, 2021). "The study's objective is to analyze these indices and C-reactive protein (CRP) to elucidate prognostic insights in COVID-19 patients at the time of admission." (PMID 33680618, 2021). "The early warning indicator for medium and critical adult patients with COVID-19 is a progressive increase in CRP; in addition, symptoms of poor breathing and dyspnea will occur due to the virus invading the lungs, and hypoxia will result in decreased SPO2H." (PMID 34504246, 2021). "Mortality predictors among severe COVID-19 patients by multivariable Cox hazard regression included treatment modality, history of comorbid diseases, increased C reactive protein, high neutrophil-lymphocyte ratio, and shorter ICU and hospital stay." (PMID 34680795, 2021). "By combining clinical symptoms—e.g., hypertension, low serum albumin, lymphopenia, elevated high-sensitivity C-reactive protein (hsC-RP)—and temporal CT scans, deep learning models were shown to outperform the human-based COVID-19 diagnosis." (PMID 34420513, 2021). "This demonstrated, for the first time that, CLC is better than plasma CRP level for assessing the odds of initial GI involvement in COVID-19 patients, which should be made aware to physicians currently managing the disease." (PMID 33526973, 2021). "IL-6 upregulates hepatic CRP production, thus suggesting the plausibility of the clinical use of this inflammatory biomarker as a prognosis predictor for COVID-19 patients." (PMID 34454452, 2021). "In line with our observations, some authors have reported that decreased counts of activated B lymphocytes along with older age, high C-reactive protein, and impaired renal function are independent predictors of mortality in patients with COVID-19." (PMID 34696395, 2021). "COVID-19 patients were characterized by high serum CRP and LDH concentrations and low lymphocyte number." (PMID 33484426, 2021). "Laboratory findings in COVID-19 are a decreased lymphocyte count and an increased CRP and high-sensitivity C-reactive protein level." (PMID 33533965, 2021). "COVID-19 patients with thrombocytopenia or serum CRP level of 15 mg/dL or higher were more likely to be admitted to ICU." (PMID 34540480, 2021). "Our study lacks suitable sample size to detect the ability of MA, CRP, D-dimer, or fibrinogen to discriminate these clinical outcomes related to hypercoagulability in COVID-19." (PMID 33641491, 2021). "This is particularly pronounced in patients with critical COVID-19, and CRP and PCT levels are increased only slightly in patients with severe and moderate COVID-19." (PMID 33832097, 2021). "C-reactive protein, serum ferritin and lactate dehydrogenase levels in persons with COVID-19 were shown in previous studies to be elevated." (PMID 34441048, 2021). "During hospitalization, leukocytes peak, platelets peak, CRP, and fibrinogen peaks were significantly higher in patient with COVID-19 (p < 0.05)." (PMID 34064556, 2021). "A 12-year-old patient, who showed fever, vomiting, abdominal pain, lymphopenia, high CRP (150 mg/dl), and G6PD deficiency with GGO chest finding, died from COVID-19." (PMID 34118894, 2021).